GSK3B (glycogen synthase kinase 3 beta)
Diseases named in the same sentence as GSK3B in open-access papers (continued):
Sharing a sentence is not in itself a finding about the gene and the disease.
colorectal cancer (163 papers, 2010 to 2025). A primary or metastatic malignant neoplasm that affects the colon or rectum. "We used proteomic and cell-biological approaches to analyse the functional consequences of loss of GSK3β in colorectal cancer cells." (PMID 34739494, 2021). "For example, it is documented that Paris saponin VII suppressed colorectal cancer cells growth through GSK-3β associated Ras signaling pathway." (PMID 34955834, 2021). "In this study, LC-MS/MS expression analysis was performed using knockout GSK3β colorectal cancer cells and isogenic controls in colorectal cancer cell lines carrying dominant stabilizing mutations of β-catenin." (PMID 34739494, 2021). "In summary, using a precision colorectal cancer cell-line knockout model with constitutively activated β-catenin we identified several of the diverse pathways and processes associated with GSK3β function." (PMID 34739494, 2021). "Deregulation of GSK-3β has been implicated in tumorigenesis and cancer progression including that of colorectal cancer." (PMID 25002914, 2014). "APC, β-catenin, axin, and GSK-3β mutations can cause increased expression of β-catenin in the cytoplasm and nucleus of colorectal carcinoma, which leads to Wnt pathway activation." (PMID 20346115, 2010). "However, a more recent study on human colorectal cancer cell lines shows that hyperactive Akt causes GSK3β inhibition and consequential β-catenin accumulation." (PMID 34064046, 2021). "The adenomatous polyposis coli protein was mainly altered in adenomas, and that, along with the increase in colorectal cancer of GSK3β, axin 1 and ubiquitin-mutated proteins, may prevent the phosphorylation of beta-catenin by the destroyer complex and its subsequent degradation in the proteasome." (PMID 27462886, 2016). "NUAK1 has been reported to inactivate glycogen synthase kinase-3 beta (GSK3β) by suppressing the de-phosphorylation pathway of GSK3β Ser9 in colorectal cancer cells." (PMID 39901136, 2025). "PKCβII potentiates tumor growth (e.g., in gastric and colorectal cancers) by activating the glycogen synthase kinase 3 beta (GSK3β) signaling axis, which enhances cellular proliferation and invasiveness." (PMID 41244006, 2025). "As an illustration, GSK3β has been reported to facilitate tumor progression in osteosarcoma and pancreatic cancer, while acting to suppress cancer development in colorectal cancer cells." (PMID 41153674, 2025). "In colorectal cancer, RPF2 is significantly overexpressed, promoting epithelial-mesenchymal transition (EMT) via the AKT/GSK-3β signaling pathway, thereby enhancing migration and invasion of colorectal cancer cells in vitro and vivo." (PMID 40577282, 2025). "GSK-3β activation has also been described in response of colorectal cancer cells to kinase inhibitors." (PMID 38284896, 2024). "Studies have shown that the expression of GSK3β is closely related to the occurrence and prognosis of colorectal cancer." (PMID 39114307, 2024). "Upon GSK-3β inhibition in different colorectal cancer (CRC) cell lines, Manzamine A induced cell cycle arrest, mitochondria-driven apoptotic cell death, and epithelial–mesenchymal transition (EMT) abolishment." (PMID 37108703, 2023). "Toosendanin, a triterpenoid extracted from the bark or fruits of Melia toosendan Sieb et Zucc inhibited growth and induced apoptosis in colorectal cancer through suppression of the Akt/GSK-3β/β-catenin pathway in vitro and in vivo." (PMID 37047425, 2023).
colorectal cancer (continued). "Zhu discovered that NOP14 regulates the NRIP1/GSK-3β/β-catenin signalling pathway to promote colorectal cancer proliferation and migration." (PMID 37441804, 2023). "In colorectal cancer cells, GSK3β binds to highly expressed PADI4 and is citrullinated at R344, promoting nuclear translocation of GSK3β from the cytoplasm to nucleus." (PMID 37777749, 2023). "MiRNA224 activates the Wnt/β-catenin signalling, down-regulates GSK3β, and promotes aggressive phenotype of colorectal cancer cells." (PMID 37670299, 2023). "On the other hand, activation of PI3K/Akt can phosphorylate glycogen synthase kinase (GSK)-3β to promote GSK-3β ubiquitination and degradation and further maintain the stability of Snail and Slug in prostate and colorectal cancers." (PMID 36766694, 2023). "Upregulation of miRNA-29a can reduce GSK3β protein expression in colorectal cancer cells and inhibit Wnt/β-catenin signaling pathway." (PMID 36210981, 2022). "AXIN2 is a negative regulator that suppresses GSK3β-mediated degradation of Snail1 and is proved to exert a promotive effect on colorectal cancer." (PMID 35470736, 2022). "BTG3 overexpression suppressed the proliferation and invasion of epithelial ovarian and colorectal cancer cells by weakening Akt/GSK3β/β-catenin signaling." (PMID 36186486, 2022). "Our results showed that PGC-1α regulated cell proliferation and invasion by regulating the LARS1/AKT/GSK3β/β-catenin axis in human colorectal cancer cells." (PMID 36612155, 2022). "Pathologies such as inflammatory bowel diseases (IBD) and colorectal cancer (CRC) are characterized by a high activity of GSK3β in epithelial cells and their microenvironment, but the etiology of this over-activity is poorly understood." (PMID 33498808, 2021). "While the importance of miR-377-3p has been demonstrated in some tumors, it was found that miR-377-3p plays an oncogenic function in colorectal cancer development through increasing GSK-3β expression and thereby activating NF-κB pathway." (PMID 33817324, 2021). "In APC-mutated colorectal cancer cells, TNKSi resulted in the accumulation of cytoplasmic puncta and β-catenin degradasomes containing TNKS1/2, AXIN1/2, APC, GSK3β, and β-catenin." (PMID 34337362, 2021). "More importantly, the new insights into the activation of EGFR/Akt/GSK3β signaling axis medicated by PRMT5 provide much new information for the mechanisms of the carcinogenic effect of PRMT5 in human colorectal cancer." (PMID 33495409, 2021). "We used an isogenic homozygous GSK3β knockout model derived from the model colorectal cancer cell line HCT116." (PMID 34739494, 2021). "VPA also triggered the EMT process of colorectal cancer cells targeting Snail via the Akt/GSK-3β pathway." (PMID 34568018, 2021). "Since the role of GSK3β in regulation of Wnt/β-catenin signalling in colorectal cancer is comparatively well understood, we have used colorectal cancer cells with constitutively stabilized and activated β-catenin to identify other GSK3β regulated processes." (PMID 34739494, 2021). "Altogether, our findings reveal that PRMT5 controls EMT through activation of the EGFR/Akt/GSK3β signaling pathway in colorectal cancer cells." (PMID 33495409, 2021). "More importantly, our results also uncover that PRMT5 promotes EMT in colorectal cancer cells via EGFR/Akt/GSK3β signaling axis." (PMID 33495409, 2021). "Mainly, miR-146a-5p promoted the growth of human osteosarcoma by targeting the ZNRF3/GSK3β/β-catenin pathway and enhanced the migration and invasion of human colorectal cancer cells by targeting the carboxypeptidase M/src-FAK pathway." (PMID 34051870, 2021). "The use of REG4 antagonists or Akt inhibitors decreased, while GSK-3β antagonist significantly increased mitotic index and proliferation in colorectal cancer cells." (PMID 33489872, 2020).
colorectal cancer (continued). "In line with our findings, in colorectal cancer, the downregulation of GSK-3-β upon FAT4 repression, while upregulation of its phosphorylated form, was observed, which was attributed to the PI3K-AKT pathway in colorectal cancer." (PMID 32366234, 2020). "GSK-3β is an important signal transduction molecule in the Wnt/β-catenin signaling pathway, and CRIP1 promotes EMT through zinc-induced p-GSK-3β in colorectal cancer." (PMID 33584272, 2020). "EGCG inhibited phosphorylation of GSK3β, upregulated GSK3β expression, and decreased the levels of β-catenin in colorectal cancer cells." (PMID 32290543, 2020). "Previously, FAK has been reported to promote Wnt signaling in colorectal cancer by phosphorylating GSK3β thereby blocking the degradation of β-catenin and its accumulation." (PMID 32493400, 2020). "In colorectal cancer cells, β-catenin regulates the activity of the NF-κB promoter, whereas inhibition of GSK-3β by lithium or siRNA potentiated TNF-induced expression of IL-6 and CCL2 in human microvascular endothelial cells." (PMID 33171974, 2020). "It was revealed that hesperidin supplementation initiated apoptosis via targeted inhibition of constitutively activated Aurora-A-mediated PI3K/Akt/GSK-3β and mTOR pathways in colorectal cancer." (PMID 31269749, 2019). "It is reported that PI3K/AKT phosphorylation occurs during viral entry, and TSN suppressed the AKT/GSK-3β/β-catenin signaling pathway in colorectal cancer cells." (PMID 31607903, 2019). "TC-HW suppressed the proliferation of human colorectal cancer cells through GSK3β-dependent cyclin D1 degradation and induced ROS-dependent apoptosis in human colorectal cancer cells." (PMID 29554905, 2018). "Diallyl disulfide (DADS) is a constituent of garlic that inactivates NFκB and prevents colitis-induced colorectal cancer via inhibition of GSK-3β signaling." (PMID 30320007, 2018). "One study showed that experimental knockdown of CD146 can dedifferentiate colorectal cancer cells to acquire a stem cell phenotype through inhibiting GSK-3β which in turn promoted nuclear translocation of β-catenin for Wnt signaling activation." (PMID 28356914, 2017). "Overall, activation of GABABR leaded to inhibition of GSK‐3β activation to repress the NF‐κB function during colorectal cancer cell proliferation." (PMID 27060477, 2016). "In summary, we uncovered that the GABABR/GSK‐3β/NF‐κB signaling pathway can regulate the proliferation of colorectal cancer." (PMID 27060477, 2016). "The main oncoprotein in colorectal cancer is the WNT pathway effector β-catenin, which transportation to the nucleus and overactivation due to genic mutations in the APC, Axin, CKI, and GSK-3β in most cases." (PMID 27613840, 2016). "Our report is also consistent with the previous findings of others who have shown that GSK-3β inhibitors are capable of suppressing the growth of a number of tumors like leukaemia, glioblastoma, breast and colorectal cancer." (PMID 27579985, 2016). "Its AKT/GSK-3β-mediated stabilization has been demonstrated to be necessary for TNF-α-induced EMT in colorectal cancer cells." (PMID 24811539, 2014). "We sought to determine the biological function of lithium, one kind of GSK-3β inhibitors, in the process of reactive oxygen species (ROS) production in colorectal cancer." (PMID 25002914, 2014). "Although recent studies suggest this drug inhibits cell cycle progression and cell proliferation via upregulating the expression of GSK-3β in different cell types, the role of lithium in the proliferation and survival of colorectal cancer remains elusive." (PMID 25002914, 2014). "The present study showed that LiCl played a critical role in the survival, proliferation, and apoptosis of colorectal cancer cell via the ROS/GSK-3β/NF-κB pathway." (PMID 25002914, 2014). "GSK-3β, known to be a survival factor for cancer, is constitutively activated in colorectal cancer cells." (PMID 25002914, 2014).
colorectal cancer (continued). "It has been reported that Galectin-3 silencing inhibits epirubicin-induced ATP binding cassette transporters and activates the mitochondrial apoptosis pathway via β-catenin/GSK-3β modulation in colorectal carcinoma." (PMID 25260879, 2014). "This mutual amplification mirrors feedback loops observed in other cancers, such as the NAT10/SEPT9/HIF-1α axis in gastric cancer glycolysis and the NAT10/KIF23/GSK-3β axis in colorectal cancer progression, underscoring the critical role of NAT10 in sustaining oncogenic signaling networks." (PMID 40999468, 2025). "Notably, TDZD-8-mediated GSK-3β inhibition induced cell death and reduced the growth of different tumor types, including colorectal cancer, leukemia, glioblastoma, prostate cancer, and ovarian cancer." (PMID 37108703, 2023). "Therefore, LiCl targets ROS/GSK3β/NF-κB pathways, resulting in increased apoptosis of colorectal cancer." (PMID 36836894, 2023). "Likewise, our study found that inhibition of MIF suppressed colorectal cancer progression by inhibiting the AKT/GSK‐3β pathway." (PMID 35567291, 2022). "Inhibition of GSK‐3β can also reduce the proliferation of colorectal cancer cells by down‐regulating NF‐κB and NF‐κB‐mediated gene expression, which may benefit the clinical outcomes of patients suffering from colorectal cancer." (PMID 35567291, 2022). "In colorectal cancer cells, active GSK3β associated with mutated APC is not efficient to promote β-catenin degradation, resulting in Wnt signaling deregulation and increased proliferation." (PMID 33498808, 2021). "TPR can promote cell proliferation in colorectal cancer via binding with GSK3β." (PMID 34384498, 2021). "Additionally, GA was also demonstrated to suppress the expression of cancer stem cells (CSC) markers as well as the β-catenin/p-GSK3β signaling in colorectal cancer." (PMID 34690755, 2021). "Finally, our findings reveal that PRMT5 promotes EMT through activation of the EGFR/Akt/GSK3β signaling pathway in colorectal cancer cells." (PMID 33495409, 2021). "In colorectal cancer cells, missense mutations are frequently found in exon 3 of CTNNB1, which encodes the N-terminal region of β-Catenin, including serine–threonine phosphorylation sites for GSK3β that induce β-Catenin degradation." (PMID 33184430, 2020). "These alterations in cell cycle profiles and in the expression of cell cycle regulatory molecules are consistent with our previous study showing that inhibition of GSK3β induced mitotic catastrophe following G2/M-phase cell cycle arrest in colorectal cancer cells, ultimately resulting in apoptosis." (PMID 32678196, 2020). "In conclusion, here we demonstrated that the inhibition of the hypoxia-induced non-coding RNA miR-675-5p hampered the nuclear localization of β-catenin by regulating GSK-3β activity, thus proposing the miR-675-5p as a new therapeutic target for the treatment of colorectal cancer." (PMID 32481626, 2020). "REG4 promotes colorectal cancer cell division through Akt/GSK-3β/β-catenin/TCF-4 pathway." (PMID 33489872, 2020). "Furthermore, HSF1 targets were upregulated by the potent GSK3β inhibitor LiCl in colorectal cancer cell line RKO, which had a low level of β-catenin expression." (PMID 32838807, 2020). "Indeed, TSN suppressed the AKT/GSK-3β/β-catenin signaling pathway in colorectal cancer cells, resulting in growth inhibition and apoptosis." (PMID 31607903, 2019). "Interestingly, GSK3β is a regulator of the Wnt signaling pathway and connections between upregulated Wnt signaling and distant metastasis in colorectal cancer have been identified." (PMID 30738427, 2019).
colorectal cancer (continued). "We found miR-452 could activate Wnt/β-catenin signaling pathway by targeting GSK3β in colorectal cancer." (PMID 30253791, 2018). "We previously discovered that PTP4A2 could activate AKT/GSK3β/β-catenin pathways to induce epithelial-to-mesenchymal transition (EMT) during colorectal cancer metastasis." (PMID 29100406, 2017). "To examine whether FILIP1L activates oncogenic signaling pathways in human colorectal cancer cells, we measured phosphorylated β-catenin, Akt, and GSK-3β protein levels, using Western blotting." (PMID 27750216, 2016). "This study revealed critical function of GABABR/GSK‐3β/NF‐κB signaling pathway on regulating proliferation of colorectal cancer cell, which might provide a potential therapeutic target for clinical colorectal cancer treatment." (PMID 27060477, 2016). "GSK3β suppresses Nur77 activity by phosphorylating Nur77 in colorectal cancer." (PMID 26840408, 2016). "Furthermore, miR-224 expression is upregulated in colorectal cancer tumor samples and is inversely correlated with GSK3β and SFRP2." (PMID 26822534, 2016). "In addition, Akt/GSK-3β/β-catenin signaling pathway activity promotes cell motility, cell survival, angiogenesis, and carcinogenesis in colorectal cancer." (PMID 27750216, 2016). "To investigate whether GABABR can regulate GSK‐3β to inhibit colorectal cancer cell proliferation and cell cycle, we performed further experiments." (PMID 27060477, 2016). "Furthermore, we found that inhibition of GSK‐3β activation, which leads to repression of colorectal cancer cell proliferation, can be rescued by upregulation of NF‐κB activation by PMA." (PMID 27060477, 2016). "We also suggest that GSK-3β could represent an interesting target for colorectal cancer therapy, in view of its central role in molecular signaling pathway cross-talk and EMT regulation." (PMID 26151224, 2015). "However, recent studies suggested that ER stress can induce GSK-3β activation, and their activation plays an important role in the proliferation of human ovarian and colorectal cancer cells." (PMID 25514597, 2014). "Taken together, our results demonstrated that therapeutic targeting of ROS/GSK-3β/NF-κB pathways may be an effective way for colorectal cancer intervention, although further preclinical and clinical testing are desirable." (PMID 25002914, 2014). "Our results suggested that GSK-3β could be a novel potential therapeutic target in the treatment of colorectal cancer and lithium should be a novel potential antitumor drug with lower price." (PMID 25002914, 2014). "The activity of GSK3b expression in colorectal cancer patients is higher than those in their normal samples and the GSK3b inhibitor may induce apoptosis in human colorectal cancer cells." (PMID 24565337, 2013). "SIX is enriched in the CD44+CD24-/low subpopulation, whereas DACH might act as a tumor suppressor to reduce the number of BCSC subpopulations in vitro and in vivo though phosphorylating GSK3β and inhibiting Wnt signaling, compliance with findings in colorectal carcinomas." (PMID 27793013, 2017). "Moreover, as we recently suggested, GSK-3β could represent an interesting target for colorectal cancer therapy." (PMID 26151224, 2015). "So we provided evidence that GSK-3β may serve as a therapeutic target in colorectal cancer." (PMID 25002914, 2014). "GSK3β is a constitutively active serine/threonine kinase featured in two signaling pathways that are of particular importance for intestinal epithelial cell proliferation and colorectal cancer: the Wnt/β-catenin pathway and the phosphatidylinositol 3-kinase (PI3K)/Akt pathway." (PMID 23919615, 2013). "For instance, in colorectal cancer, TBX21 inhibits the proliferation of tumor cells and promotes their apoptosis by regulating the ARHGAP29/RSK/GSK3β signaling pathway." (PMID 41573646, 2025).